MTA3 (metastasis associated 1 family member 3)
Description:
Acts as a component of the histone deacetylase NuRD complex which participates in the remodeling of chromatin. Plays a role in maintenance of the normal epithelial architecture through the repression of SNAI1 transcription in a histone deacetylase-dependent manner, and thus the regulation of E-cadherin levels. Contributes to transcriptional repression by BCL6.
Synonyms: KIAA1266
Tractability: PROTAC: ubiquitination databases record sites on it; its protein half-life has been measured.
Gene: Protein-coding gene on chromosome 2 (42,494,569 to 42,756,947, forward strand). Ensembl gene ENSG00000057935.
Subcellular location: Nucleus; Cytoplasm
Subcellular location (Human Protein Atlas): Nucleoplasm; Vesicles
Pathways (Reactome):
Gene expression (Transcription): ERCC6 (CSB) and EHMT2 (G9a) positively regulate rRNA expression; RNA Polymerase I Transcription Initiation; Regulation of endogenous retroelements by KRAB-ZFP proteins; Regulation of endogenous retroelements by Piwi-interacting RNAs (piRNAs)
Chromatin organization: HDACs deacetylate histones; Interaction of NuRD complexes with transcription factors; NuRD complex assembly
Developmental Biology: Differentiation of naive CD4+ T cells to T helper 2 cells (Th2 cells); Transcriptional regulation of brown and beige adipocyte differentiation by EBF2
Disease: Potential therapeutics for SARS
Signal Transduction: Regulation of PTEN gene transcription
Gene Ontology:
Molecular function: protein binding; histone deacetylase binding; transcription coactivator activity; transcription corepressor activity; chromatin binding; sequence-specific DNA binding
Biological process: chromatin remodeling; negative regulation of DNA-templated transcription; negative regulation of transcription by RNA polymerase II; positive regulation of DNA-templated transcription; regulation of cell fate specification; regulation of stem cell differentiation; regulation of DNA-templated transcription
Cellular component: nucleoplasm; nucleus; NuRD complex; cytoplasm
Genetic constraint (gnomAD): Loss-of-function variants: 20 observed, 47.3 expected, observed/expected ratio (o/e) 0.42, 90% interval 0.3 to 0.61. The upper end of that interval is the gene's LOEUF score, 0.61, which puts it in group 2 of 6, group 1 being the genes least tolerant of losing a copy. Missense variants: 548 observed, 533.14 expected, observed/expected ratio (o/e) 1.03, 90% interval 0.96 to 1.1. Synonymous variants: 216 observed, 187.4 expected, observed/expected ratio (o/e) 1.15, 90% interval 1.03 to 1.29.
Homologues: Orthologues: chimpanzee MTA3 (100% identical), macaque MTA3 (98% identical), rabbit MTA3 (95% identical), rat Mta3 (95% identical), mouse Mta3 (93% identical), pig MTA3 (91% identical), guinea pig MTA3 (87% identical), zebrafish mta3 (69% identical), Drosophila melanogaster MTA1-like (54% identical). Paralogues in human: MTA1 (70% identical), MTA2 (64% identical), MIER2 (17% identical), MIER3 (17% identical), MIER1 (14% identical).
Diseases named in the same sentence as MTA3 in open-access papers:
MTA3 is named in the same sentence as 52 diseases in open-access papers, as found by Europe PMC text mining. Sharing a sentence is not in itself a finding about the gene and the disease. The quoted sentences say what the papers report.
breast carcinoma (28 papers, 2007 to 2025). "In certain types of malignant tumors such as glioma, certain breast cancers, and adenocarcinomas, MTA3 is under-expressed and is implicated as a tumor suppressor." (PMID 31149338, 2019). "On the other hand, earlier studies in breast cancer showed that ERα promoted metastasis-associated family member 3 (MTA3)–dependent repression of Snail and E-cadherin expression." (PMID 29996493, 2018). "Studies have confirmed that ER levels can affect the invasive and metastatic phenotype of breast cancers by regulating the expression of E-cad via the ER-metastasis-associated protein MTA3-Snail-E-cad signaling pathway." (PMID 28764784, 2017). "The downregulation of MTA3 was reported in breast cancer, endometrial cancer and ovarian cancer, while the upregulation of MTA3 expression has been implicated in human chorionic cancer." (PMID 23840517, 2013). "MTA3 expression is significantly associated with breast cancer prognosis." (PMID 41584603, 2025). "The results showed that MTA3 protein expression had a positive association with that of E-cadherin and cytoplasmic β-catenin and that MTA3 protein expression was progressively reduced during breast cancer progression." (PMID 28279208, 2017). "In contrast to its tumor-suppressive function in breast cancer, MTA3 is frequently overexpressed in CRC and is significantly associated with advanced TNM stage, elevated Ki67 index, and poor prognosis." (PMID 41584603, 2025). "Currently, the majority of research concerning MTA3 in breast cancer remains at the preclinical exploration and early translational stages." (PMID 41584603, 2025). "Our previous study showed that NuRD (MTA1) and NuRD (MTA3) form an antagonism that potentially regulates breast cancer development and progression." (PMID 39154024, 2024). "Migration assays revealed that MTA1 overexpression or MTA3 knockdown resulted into an increase in the migration of breast cancer cells, whereas MTA1 knockdown or MTA3 overexpression induced the opposite effect." (PMID 39154024, 2024). "The EdU assays in breast cancer cells showed that the decrease in proliferation mediated by MTA1 knockdown was reversed by MTA3 or TRIM21 knockdown." (PMID 39154024, 2024). "Gene Expression Omnibus (GEO) datasets analysis indicated that MTA1 expression was upregulated in breast cancer, MTA3 expression was decreased in breast cancer." (PMID 39154024, 2024). "Growth curve analysis showed that MTA1 significantly promoted breast cancer cell growth, whereas MTA3 inhibited cell growth." (PMID 39154024, 2024). "In summary, the invasion of breast cancer was impeded through the activation of the FOXO3a/ERα/MTA3/E-cadherin pathway by EGCG." (PMID 38505423, 2024). "Together, these results suggest that MTA1 promotes EMT and stemness in breast cancer, while MTA3 exerts an opposite effect." (PMID 39154024, 2024). "MTA1 overexpression or MTA3 knockdown promoted breast cancer invasion, whereas knockdown of MTA1 or MTA3 overexpression had the opposite effect." (PMID 39154024, 2024). "The findings indicated that MTA1 expression was significantly upregulated in breast cancer tissues compared to that in normal tissues, whereas MTA3 and TRIM21 were the opposite." (PMID 39154024, 2024). "MTA1-overexpression promoted the invasiveness of breast cancer cells, while overexpression of MTA3 or TRIM21 restored it to normal levels." (PMID 39154024, 2024). "The 5-ethynyl-2′-deoxyuridine (EdU) results showed that MTA1 knockdown or MTA3 overexpression caused a significant decrease in EdU-labeled breast cancer cells, and MTA1 overexpression or MTA3 knockdown caused the opposite effect." (PMID 39154024, 2024). "The crosstalk between MTA1 and MTA3 regulates the malignancy of breast cancer cells, including proliferation, invasion, EMT, and stemness." (PMID 39154024, 2024). "The results demonstrated that MTA1 expression was significantly increased in breast cancer tissues, while MTA3 expression was higher in adjacent tissues." (PMID 39154024, 2024).
breast carcinoma (continued). "We found that MTA1 and MTA3 are recognized by specific transcription factors and play opposing roles in breast cancer." (PMID 39154024, 2024). "MTA1 overexpression or MTA3 knockdown increased colony numbers with the comparison of vector group or shScramble (shSCR), whereas MTA1 knockdown or MTA3 gain-of-function decreased this effect in breast cancer cells." (PMID 39154024, 2024). "MTA3 is generally identified as an estrogen-inducible gene product that is strictly regulated by estrogen receptor α (ER-α)-positive breast cancer cell lines." (PMID 36050478, 2022). "MTA1 and MTA2 have both been reported to be pivotal for epithelial-mesenchymal transition (EMT) and metastasis of breast cancer, while MTA3 has been reported to inhibit EMT." (PMID 30642362, 2019). "Specifically, several subunits of NuRD, such as MTA1, MTA3, and Mi-2 can directly control the cancer invasive growth, epithelial-to-mesenchymal transition, and metastasis in breast cancer." (PMID 29625565, 2018). "Nevertheless, in opposite to MTA1 and MTA2, MTA3 was reported to have different expression pattern and function in human malignancies, which was first identified in human breast cancer." (PMID 28418887, 2017). "MTA3 was originally identified as a corepressor that inhibits breast cancer cell EMT, invasion, and metastasis, and its protein expression is gradually decreased during progression in breast cancer tissues." (PMID 28279208, 2017). "Because MTA3 is a cell type-specific component of the NuRD complex, and MTA3 expression depends on estrogen action, MTA3 regulates EMT and cancer metastasis of breast cancer via the ER-MTA3/NuRD/Snail/E-cadherin pathway." (PMID 28279208, 2017). "The expression level of MTA3 was found to be decreased in human malignancies including ovarian cancer, breast cancer and endometrial cancer." (PMID 28418887, 2017). "Lysine-specific demethylase-1 (LSD1) is a physical integral component of the MTA3/NuRD complex in vivo; the LSD1/MTA3/NuRD complex targets TGFβ1, then inhibits the invasiveness in vitro and suppresses metastatic potential in vivo in breast cancer." (PMID 28279208, 2017). "Since then, however, the expression of MTA3 has found to be reduced in breast cancer, endometrial cancer and ovarian cancer." (PMID 23840517, 2013). "Since then, however, the expression of MTA3 has been found reduced in breast cancer, endometrial cancer and ovarian cancer." (PMID 24107548, 2013). "MTA3 was initially identified in breast cancer as an estrogen receptor (ER)-regulated inhibitor involved in the ER-dependent downregulation of the Snail-mediated inhibition of E-cadherin." (PMID 23671646, 2013). "MTA3 exhibits significant tumor-suppressive effects in breast cancer." (PMID 41584603, 2025). "For example, SIX3/LSD1/NuRD(MTA3) complex suppresses breast cancer initiation and metastatic progression; GATA3/G9A/NuRD(MTA3) complex inhibits tumor invasion in both in vitro and in vivo models, and its downregulation leads to ZEB2 upregulation and promotes malignant progression." (PMID 41584603, 2025). "In neoplastic conditions, such as breast cancer, MTA3 primarily acts as a tumor suppressor." (PMID 41584603, 2025). "MTA1 expression was significantly negatively correlated and MTA3 expression in breast cancer." (PMID 39154024, 2024). "On the one hand, the biological characteristics of MTA3 in breast cancer have been recognized." (PMID 36050478, 2022). "Furthermore, it has been reported that MTA3 exhibits a specific ER-dependent expression pattern in the development and progression of primary breast cancers." (PMID 36050478, 2022). "One of the typical members of the GATA family, GATA3, was reported to interact with G9A/NuRD(MTA3) to suppress breast cancer metastasis through targeting the promoters of an array of genes involved in important cellular signaling pathways regulating cell migration and invasion." (PMID 30563971, 2018).
breast carcinoma (continued). "MTA3 was identified as a component of Mi2/NuRD complex and transcriptional corepressor, which is dependent on estrogen and negatively regulate gene expression in breast cancer cells." (PMID 28279208, 2017). "In breast cancer, MTA3 was demonstrated to could enhance cell-cell adhesion and inhibit tumor cell invasion and metastasis by its inhibition on Snail and E-cadherin." (PMID 28418887, 2017). "Since a role of Wnt signaling for breast cancer metastasis has been described, it is reasonable to speculate that MTA3 might inhibit metastasis via suppressing Wnt signaling." (PMID 28279208, 2017). "Recently, accumulating evidence showed that MTA3 could regulate cell proliferation and differentiation in various cancers and act as an oncogene in breast cancer and non-small cell lung cancer (NSCLC)." (PMID 28968973, 2017). "MTA3 has been described as a master regulator of EMT in human breast cancer cells." (PMID 23671646, 2013). "The metastasis-associated gene MTA3, a novel component of the Mi-2/NuRD transcriptional repression complex, was identified as master regulator of EMT through inhibition of Snail to increase E-cadherin expression in breast cancer." (PMID 23671646, 2013). "MTA3 also interacts with proteins such as MTA1 and TRIM21 to regulate breast cancer stemness and EMT, and this regulatory equilibrium is modulated by estrogen signaling." (PMID 41584603, 2025). "Conversely, MTA3 inhibited MTA1 transcription and TRIM21 regulated MTA1 protein stability in breast cancer." (PMID 39154024, 2024). "Our findings revealed that TRIM21 affects the stability of MTA1 to hinder breast cancer proliferation, invasion, EMT, and cancer stemness and synergizes with MTA3 to maintain epithelial homeostasis." (PMID 39154024, 2024). "The protein complex GATA3/G9A/MTA3 represses ZEB2, and other genes involved in EMT, leading to suppression of metastasis from human breast cancer cells in mice." (PMID 39242600, 2024). "To further explore the predictive performance of MTA1, MTA3, and TRIM21 in the prognosis of patients with breast cancer, we performed immunohistochemical staining." (PMID 39154024, 2024). "As FOXA1 had the most significant gene expression, we checked the correlation between FOXA1 and other diabetes-related genes such as PAK4, FGFR3, MTA3, and KIF22 using a database containing 3262 ER+/PR+ breast cancer patient tissue samples." (PMID 39000600, 2024). "Among the diabetes-related genes, FOXA1, MTA3, PAK4, FGFR3, and KIF22 were highly expressed in HR+ breast cancer from 4032 breast cancer patient tissue samples using the Breast Cancer Gene Expression Omnibus." (PMID 39000600, 2024). "Our study identified multiple regulators of breast cancer stemness and showed that MTA1 influences the cancer stem-like state by interacting with EMT and inhibiting the expression of MTA3 and TRIM21." (PMID 39154024, 2024). "Transfection of FLAG-ERα contributed to the upregulated expression of TRIM21 and MTA3 and led to the decreased expression of MTA1 in breast cancer cells." (PMID 39154024, 2024). "Estrogen disrupted the balance between MTA1 and MTA3, as well as between MTA1 and TRIM21, thereby affecting stemness and the EMT processes in breast cancer." (PMID 39154024, 2024). "By contrast, in breast cancer cells, GATA3, G9A, and NuRD (MTA3) act in a coordinated manner to form a transcription-repression complex that regulates mammary epithelial plasticity by controlling EMT-related gene expression." (PMID 31685800, 2019). "Taken together, these studies suggest a mutual functional repression between Notch1 and ERα signaling in breast cancer EMT, where ERα-responsive genes (e.g., MTA3) would repress the expression of EMT-transcription factors laying downstream the Notch pathway." (PMID 29996493, 2018). "The authors postulated a new mechanism in MTA3-mediated control of EMT and cell invasion in breast cancer." (PMID 28279208, 2017).
breast carcinoma (continued). "Any regulated reduction in the level of MTA3 will lead to up-regulation of Snail, enhancement of EMT, and metastasis of breast cancer." (PMID 28279208, 2017). "MTA3 upregulation prevents EMT by directly repressing Snail expression, thereby upregulating E-cadherin protein levels in breast cancer." (PMID 23840517, 2013). "The ER induced inhibitor of SNAIL1, MTA3, and GATA3, which inhibits breast cancer metastasis through the reversal of EMT, were also significantly lower." (PMID 21713035, 2011). "In this study, we aimed to investigate the roles of MTA1, MTA3, and tripartite motif-containing 21 (TRIM21) in the proliferation, invasion, epithelial-mesenchymal transition (EMT), and stem cell-like properties of breast cancer cells in vivo and in vitro." (PMID 39154024, 2024). "However, the mechanisms by which MTA1 and MTA3 play important roles in stem cell-like properties and EMT in breast cancer remain poorly understood." (PMID 39154024, 2024). "MTA3 and TRIM21 are potential prognostic biomarkers for breast cancer." (PMID 39154024, 2024). "MTA3 expression is progressively downregulated in breast cancer, and the absence of MTA3 promotes disease progression in breast cancer." (PMID 39154024, 2024). "As a regulator of epithelial-mesenchymal transition, ZEB2 is strongly downregulated by miR-221, and ZEB2 expression was increased, which in turn inhibited the expression of G9A and MTA3 by recruiting G9A/NuRD (MTA1), thereby promoting the metastasis and progression of breast cancer." (PMID 36072677, 2022). "MTA3 upregulation prevents epithelial-mesenchymal transition (EMT) by directly repressing Snail expression, thereby upregulating E-cadherin protein levels in breast cancer." (PMID 24107548, 2013). "Besides the MTA-3 pathway (ZR75-1), HSPB1, an ATP-independent chaperone with the hsp20-like chaperonedomain, operates in multiple pathways like the breast cancer estrogen signaling pathway (MCF-7, ZR75-1)." (PMID 17883861, 2007). "Five of the 14 diabetes-related genes, FOXA1, KIF22, PAK4, MTA3, and FGFR3, were specifically highly expressed in only the ER+/PR+ and ER+/PR− subtypes but not ER−/PR+ and ER−/PR− through an analysis using 4032 patient tissue samples from Breast Cancer Gene Expression Miner v4.5." (PMID 39000600, 2024). "Besides, researchers found that expression of Six3 is negatively correlated with breast cancer malignancy and further studies on the mechanism revealed that Six3 recruits LSD1/NuRD(MTA3) complex to Wnt1 promoters, thus resulting in a reduction of Wnt1 expression levels in breast cancer." (PMID 34545072, 2021). "In conclusion, our research provides mechanistic understandings that the negative feedback loops between MTA1 and MTA3, MTA1, and TRIM21 in response to estrogen are initiated to regulate cancer stem cell fate and EMT in breast cancer." (PMID 39154024, 2024).
glioma (8 papers, 2017 to 2025). A benign or malignant brain and spinal cord tumor that arises from glial cells (astrocytes, oligodendrocytes, ependymal cells). "MTA3 is downregulated in glioma tissues, and its low expression is independently associated with higher WHO grades and unfavorable patient prognosis, indicating a potential tumor-suppressive function." (PMID 41584603, 2025). "In forthcoming preclinical research, it is imperative to conduct an in-depth investigation into the regulatory network and molecular mechanisms of MTA3 in glioma." (PMID 41584603, 2025). "The observed mechanism is for lncRNA HCG11 to suppress growth of glioma was by acting with the miR-4425 to release MTA3." (PMID 33926464, 2021). "Given that the malignancies such as glioma, ovarian cancer, and endometrial cancer have nature of invasive and migration, further studies are required to elucidate how MTA3 regulates the EMT and metastasis in these cancers." (PMID 28279208, 2017). "HCG11 suppresses the growth of glioma by interaction with miR-4425 to express MTA3." (PMID 35432537, 2022). "Additionally, HCG11 has been proposed to suppress the growth of glioma through cooperating with miR-4425/MTA3 axis." (PMID 34054958, 2021). "Similarly, lncRNA HCG11 has been reported to suppress the growth of glioma through cooperating with miR‐4425/MTA3 axis." (PMID 32844573, 2020). "MTA3 is underexpressed in glioma, ovarian cancer, and endometrial cancer." (PMID 28279208, 2017). "The PARP inhibitor olaparib exhibits dose-dependent inhibition of glioma cell migration by upregulating MTA3 and E-cadherin, downregulating multiple pro-metastatic proteins, and modulating diverse signaling pathways, highlighting its potential as a therapeutic candidate for glioma treatment." (PMID 41584603, 2025).